STAT1 (signal transducer and activator of transcription 1)
Diseases named in the same sentence as STAT1 in open-access papers (continued):
Sharing a sentence is not in itself a finding about the gene and the disease.
tumor (continued). "Reflecting its role in immunity, particularly anti-viral immunity, STAT1 generally acts as a tumor suppressor." (PMID 38022653, 2023). "Among these, upregulation of Stat1 expression was most significant within the tumor cells themselves." (PMID 38304252, 2023). "The powerful activities of interferon γ, as the prime inducer of PD-L1 expression, were found to be mediated by STAT3, and in addition, STAT1 activation was found to up-regulate the expression of PD-L1 by tumor cells." (PMID 37830552, 2023). "To further investigate the underlying mechanism of co-treatment therapy, we examined several major downstream signaling molecules of tyrosine kinases, including Stat1 and Stat3, in tumor tissues isolated at the end of the pharmacodynamic assay." (PMID 37375842, 2023). "The expression of TET2/3 and p-STAT1/3 was also increased in tumor tissue in the α-KG + anti-PD1 group." (PMID 36854755, 2023). "The marked repression of tumor growth was accompanied by the enhanced promotion of tumor p-STAT-1 and CD3+ T cell infiltrates." (PMID 37500611, 2023). "The most spliced gene was SNHG17 with >25 splice forms and tumour associated splice events of CD44, STAT1, FAS, and IRF1 further confirming the JAK-STAT pathway enrichment from GSEA." (PMID 37091785, 2023). "When ctDNA detection was combined with the level of tumour mutational burden (TMB) and a tumour-derived interferon signature (including HLA-DRA, CXCL9/10/11, GZMA, PRF1, CCR5, IFNG, IDO1 and STAT1), the predictive value of the combined score was enhanced." (PMID 38201222, 2023). "In this study, we found that ESCO2 mediates tumor progression potentially by affecting STAT1 signaling." (PMID 37968576, 2023). "Studies have reported that TIM-3 regulates tumors by STAT1, and the transcriptional function of STAT1 selectively regulates mRNA translation to regulate tumor proliferative and prosurvival properties." (PMID 36865498, 2023). "STAT1 plays a distinct role with STAT3 in IL-11-mediated osteoclastogenesis in the tumor microenvironment." (PMID 36593458, 2023). "Immunofluorescence assays show that STAT1 protein is reduced in both tumor and host cells of Rhamm−/− primary tumors and lung metastases." (PMID 37349798, 2023). "Others have demonstrated that JAK2/STAT1 inhibition in combination with enzalutamide decreases the CXCR7-driven CRPC tumor growth." (PMID 37347559, 2023). "STAT1 is a vital component of the JAK/STAT tumor-regulating signaling pathway, which can regulate cell cycle, immune response and antigen processing." (PMID 37483517, 2023). "We therefore confirmed that exposure to H2O2 at levels that damage DNA, activate interferon signaling as detected by increasing STAT1 nuclear localization in RHAMM+/+ tumor cells." (PMID 37349798, 2023). "Two datasets indicated an increasing level of STAT1 in tumor tissues with a FC of 3.207 and 3.209, respectively (all, P < .05)." (PMID 36862902, 2023). "Collectively, these results suggest that ECM-induced biomechanical force promotes tumor cell quiescence through DDR2/STAT1 signaling." (PMID 37369642, 2023). "Together, these findings highlighted the STAT1’s tumor-promoting role in HPC and indicated its involvement in ESCO2-mediated HPC development." (PMID 37968576, 2023). "Mediated by YTDHF2, METTL3/METTL14 knockdown stabilizes STAT1 and Irf1 mRNAs, and promotes IFN‐γ‐STAT1‐Irf1 signaling, which in turn sensitizes tumor cells to PD‐1 inhibition." (PMID 36810108, 2023). "Activation of the IFNγ/STAT1/IRF1 axis favors processing and the presentation of tumor antigens, in association with MHC class I or class II molecules." (PMID 36911202, 2023).
tumor (continued). "We found that MAP2K6, MAP3K5, MAP3K9, MAP3K12, RPS6KA2, RPS6KA5, and STAT1 were lowly expressed in tumor tissues; However, NFKB1, RAC1, SHC1, and TRAF2 are highly expressed compared to normal tissues." (PMID 36969076, 2023). "First, our studies with kifunensine demonstrated that the activation of STAT3 and STAT1 was effectively down-regulated by the inhibitor, alongside with a reduced tumor cell pro-metastatic functions." (PMID 37830552, 2023). "As with the deletion of PTPN2 in T cells, we found that the systemic administration of Compound 182 and the repression of AT3-OVA tumor growth also increased p-STAT-1 staining within the tumor, as well as the abundance of CD3ε+ T cells." (PMID 37500611, 2023). "Specifically, the authors determined that STAT1 is upregulated in CRC tumor tissues isolated from human subjects and azoxymethane (AOM)/dextran sodium sulfate (DSS)-induced CRC mouse models." (PMID 37173951, 2023). "On the other hand, based on its anti-proliferative and pro-apoptotic effects, STAT1 is generally regarded to have tumor-suppressive functions and in CRC, its activity was shown to be associated with a favorable prognosis." (PMID 36982677, 2023). "In this study, the pre-treatment protein expression levels of CD8, PD-L1, LAG-3, and STAT-1 proteins within the HCC tumor microenvironment were determined using multiplex immunohistochemistry/immunofluorescence (mIHC/IF)." (PMID 37342338, 2023). "STAT1 was up-regulated in most tumor types except for KICH, while STAT5B was down-regulated in almost all TCGA tumor samples except for CHOL." (PMID 36968603, 2023). "Using intravital imaging of the bone marrow, we confirmed that injection of recombinant IFN-γ in mice with established tumors resulted in STAT1 translocation in most tumor cells." (PMID 37248395, 2023). "STAT1 is a tumor suppressor gene that plays an essential role in apoptotic and anti-apoptotic signaling." (PMID 36765810, 2023). "Mechanistically, we demonstrated that the entry of M1 virus was accelerated via an increase in its binding to the Mxra8 receptor and that the evolved M1 virus overcame the antiviral response by inhibiting the activity of PKR and STAT1 in tumor cells." (PMID 37296165, 2023). "Our findings suggest that IFN-γ promotes tumor immune escape by transcriptionally activating TINCR via STAT1, which in turn upregulates PD-L1 expression." (PMID 36725842, 2023). "In contrast, excessive stress promoted the transition to quiescent status in stem cell-like tumor cells through DDR/STAT1/P27 signaling." (PMID 37369642, 2023). "In vitro studies demonstrate type II IFN-induced STAT1 activation results in upregulation of PD-L1 expression on tumor cells, thereby inhibiting T cell and natural killer cell-mediated tumor cell killing." (PMID 37561163, 2023). "We found that the deletion of PTPN2 in T cells resulted in robust p-STAT-1 within the nuclei of AT3-OVA tumor cells; both the number of p-STAT-1 positive tumor cells and p-STAT-1 intensity were increased by the deletion of PTPN2 in T cells." (PMID 37500611, 2023). "It has also been shown that integrin β1 (ITGB1) is upregulated in EOC and promotes proliferation of tumor cells by inducing STAT1 expression." (PMID 37173951, 2023). "The induction of the IDO1-Kyn-AhR axis by p27 prevents IFN-γ-induced STAT1 signaling-mediated tumor cell apoptosis and activates the dormancy program in TRCs." (PMID 37380989, 2023). "TNFα is reported to synergize with IFNγ to induce Jak1/Stat1-dependent tumor cell death and recruit cytolytic T cells to the tumor microenvironment." (PMID 36968224, 2023).
tumor (continued). "The enhanced repression of tumor growth was accompanied by increased tumor STAT-1 signaling, as reflected by the increased expression of STAT-1 target genes, including Cd274 (encodes PD-L1)." (PMID 37500611, 2023). "The repression of AT3 tumor growth was accompanied by increases in STAT-1 signaling, the expression of STAT-1 target genes, such as Cxcl9 and Cd274, the recruitment of T cells, and the re-sensitization of otherwise resistant AT3 tumors to PD-1 immunotherapy." (PMID 37500611, 2023). "The increased expression of Stat1, Ido1, and H2ab1 suggested that the IFNγ signal in the tumor was upregulated and accompanied by elevated IFNγ expression in CTLs." (PMID 36793737, 2023). "Furthermore, our results may allow us to test whether engineering the IFN-γR/JAK1/STAT1 signaling pathway in APCs could be of value in achieving a more efficient presentation of endogenous tumor–associated peptides to CD4+ T cells and potentially enhancing tumor responses." (PMID 36445781, 2023). "Increased p-CREB and p-STAT1 levels in tumour-infiltrating CD8+ T cells in B16F10 tumours from syngeneic mice fed on TVA were confirmed by flow cytometry analysis." (PMID 37993715, 2023). "Several studies have indicated that activation of STAT1 plays a tumor suppressor role in cancer cells." (PMID 37762313, 2023). "Correspondingly, STAT1 expression, as well as its functions in tumor development, has been reported to be regulated by protein ubiquitination." (PMID 36899018, 2023). "STAT1 can enhance the anti-tumor effect of immune cells and it mediates anti-angiogenic effects in endothelial cells." (PMID 38022653, 2023). "This implies that either decreasing STAT1 activity by JAKi to block expression of immunosuppressive molecules (including PARP14) or boosting STAT1 by PARP14i to enhance tumour immunogenicity are both viable approaches to increasing response to α-PD-1 therapy." (PMID 37752135, 2023). "In tumor cells, STAT1 directs cytostatic and cytotoxic effects as well as immune stimulatory effects such as increased Major histocompatibility complex (MHC) expression." (PMID 38022653, 2023). "The activation of STAT1-related antiviral immunity and the restoration of tumor suppressive TF activities of HEYL and PITX1 would synergistically contribute to the anti-tumor effects of 5-AZA-CdR treatment." (PMID 36882403, 2023). "These metagene clusters (HCK, Interferon, MHC-I, MHC-II, IgG, LCK, and STAT1) have previously been reported to represent various tumor inflammatory activities." (PMID 36439943, 2022). "LC-MS/MS analysis quantified αS1-casein protein in human milk that functions as a tumor suppressor through upregulation and hyperactivation of signal transducer and activator of transcription 1 (STAT1) signaling." (PMID 36278695, 2022). "While IL-23 inhibits ferroptotic host cell death, some cytokines, such as IFNγ, drive ferroptosis via STAT1 signaling in tumor cells." (PMID 36138043, 2022). "Combined with previous studies, these data suggest that during HNSCC, induction of PD-1 expression on T cells is partly dependent on STAT1 expression by tumour cells." (PMID 35595823, 2022). "The anti-tumor immune response is dominated by two of these factors, STAT1 and STAT2, which act by inducing type I and type II interferons (IFN)." (PMID 35330716, 2022). "Several studies suggested this tumor-promoting function to be related to STAT1-mediated regulation of PD-L1 expression." (PMID 35456965, 2022). "Together, these results suggested that the GZMA-F2R communication suppressed the tumor by promoting the activation of JAK2/STAT1 signaling pathway." (PMID 35256589, 2022). "In the greatest number of tumors, STAT4 was correlated with tumor growth, then STAT1, STAT3, STAT6, STAT5B, STAT2, and STAT5A." (PMID 36176415, 2022). "STAT1 is generally considered a tumor suppressor because it plays an essential role in the immune response and protects against pathogen infections." (PMID 35313878, 2022).
tumor (continued). "At the primary tumour site, we found that Gzmb, Ifng, and Cxcl9 transcripts were significantly reduced in carcinogen-induced Stat1−/− compared to Stat1+/+ mice." (PMID 35595823, 2022). "Apigenin not only reduced the expression of different tumor-causing genes such as TNF-α, IL-6 and CD40, but also increased the activity of the tumor-suppressing STAT1 gene via IFN-γ gene inhibition." (PMID 35807549, 2022). "STAT1 and PD-L1 were both significantly upregulated in GC tissues compared with normal tissues, and the expression of STAT1 and PD-L1 in tumor tissues were highly correlated." (PMID 35456965, 2022). "Flow cytometry showed the increase of DCs and macrophages in irradiated tumor tissues with the administration of STAT1 or CD39 inhibitor comparing to IR alone, and IHC consistently verified the increased number of infiltrating DCs." (PMID 36245000, 2022). "It is brought to our attention that STAT1 is usually considered a tumor suppressor, while increasing evidence suggests that it can also act as a tumor promoter." (PMID 35646925, 2022). "The in vivo anti‐tumour activity of JAK or STAT1 inhibitors was examined in clinically relevant t‐CRPC model." (PMID 35908276, 2022). "STAT1 is generally considered to function as a tumor suppressor, but there is growing evidence showing that STAT1 can also act as a tumor promotor." (PMID 35456965, 2022). "STAT1 is generally considered as a tumor suppressor, and the activation of STAT1 has been confirmed to induce the apoptosis of porcine GCs." (PMID 36499045, 2022). "Taken together, our findings suggest that tumour-derived STAT1 is required for PD-1/PD-L1 immune checkpoint expression and immune suppression during experimental HNSCC in vivo." (PMID 35595823, 2022). "The effects of different CYLD splice variants and the ratio of these variants on STAT1 accrual and signaling in CRC tumor cells merit future investigation." (PMID 36531014, 2022). "This is particularly significant since STAT1 mediates tumour promoting and inhibitory roles in HNSCC cells despite playing a significant anti-tumour function in immune cells." (PMID 35595823, 2022). "STAT1, STAT3 and STAT5 also possess tumour suppressive action in certain mutational and cancer type context." (PMID 35229974, 2022). "STAT1 signaling acts as a tumor suppressor by inhibiting angiogenesis, tumor growth, metastasis, and promoting apoptosis." (PMID 35719940, 2022). "Previous work from our group demonstrated that in STAT1-sufficient murine HNSCC cells orthotopically injected into Stat1+/+ and Stat1−/− mice, tumour growth is significantly enhanced when Stat1 is deleted in host tissue." (PMID 35595823, 2022). "As any abnormality or change in signal regulatory factors can lead to tumor formation, the role of STAT1 in the occurrence and development of tumors requires further study." (PMID 35692770, 2022). "STAT1 is mainly involved in antiviral and antibacterial reactions, inhibits tumor growth, and induces cell apoptosis by regulating anti-apoptotic genes such as Bcl-XL, caspases, and Bax." (PMID 35692770, 2022). "The modulated macrophages by caerin 1.1/1.9 show significant activation of Type I interferons response and Stat1 signalling, rendering animals resistant to further tumour challenges." (PMID 36497272, 2022). "If we inactivate IFN-γ, the M1 macrophage will transit to a cycle attractor M0/M2c/M2c/M0 losing the anti-tumor properties because of the inactivation of STAT1." (PMID 36544764, 2022). "The close relationship between the CRC stages and expression levels of STAT1/3/4/5B reveals their potential as molecular biomarkers for tumor stage classification." (PMID 36061181, 2022). "It has been suggested that STAT1 serves as a tumor suppressor by promoting the expression of p21waf, caspase 3 and caspase 7 to activate pro-apoptotic pathways." (PMID 35174205, 2022).
tumor (continued). "In solid tumors, STAT1 is generally considered as a tumor suppressor but there is growing evidence that STAT1 also has a pro-tumorigenic function, perhaps in a cell-type specific context." (PMID 35844493, 2022). "High glucose environment can induce hepatoma cells to up-regulate the expression of HKDC, which can promote the proliferation, invasion and metastasis of tumor cells by downregulating the HKDC/JAK2/STAT1/caspase-3 signaling pathway." (PMID 35784761, 2022). "STAT1 mediated cellular responses to cytokines and inhibited T cell exhaustion, which promoted anti-tumor immune responses in HNSC." (PMID 35222540, 2022). "The tumor volume in STAT1-RNAi combined with 125I alone or in combination with EPI was 1212.240 ± 96.013 and 921.160 ± 45.790 mm3." (PMID 35692770, 2022). "There is therefore a strong rationale to exploring TRIM24 as a target in HNSCC treatment, which can potentially leverage the STAT1 pathway to improve HNSCC tumour outcomes." (PMID 35595823, 2022). "A large body of evidence has been provided about STAT1 inhibiting proliferation and promoting apoptosis of tumor cells, and it is considered a potential tumor inhibitor." (PMID 36311733, 2022). "Phosphorylated Stat1 (pStat1) was seen as small foci of DAB + nuclei in all stages of tumor progression and quantification using QuPath suggested that some MT animals expressed higher pStat1, as reported in non-PyMT animals." (PMID 35505346, 2022). "The IFN-γ/Stat1/IRF-1 axis plays an essential role in the communication between the tumor and the microenvironment." (PMID 36284313, 2022). "Accordingly, SUMOi induced STAT1 transcript and protein expression, thus priming tumor cells for response to type II IFN." (PMID 35499080, 2022). "This showed that the tumor suppression ability of siglec-15 silencing was counteracted by STAT1 overexpression and STAT3 overexpression." (PMID 35769818, 2022). "Since STAT1 is upregulated in both primary and metastatic CRC tumor tissues, the role of STAT1 in CRC tumor growth was studied." (PMID 35313878, 2022). "We next explored PD-L1 expression in the same tissue samples, as it was previously shown that STAT1 regulates its expression in other tumor types." (PMID 35456965, 2022). "HCC (N = 124) and CCA (N = 138) tumor tissue microarrays were stained for STAT1 and STAT3 using immunohistochemistry." (PMID 35267462, 2022). "Our previous study showed that Δ9-THC can induce angiogenesis and tumor progression in CRC through activation of STAT1." (PMID 35313878, 2022). "We further analyzed the tumor-upregulated target proteins of STAT1 and STAT2, and found these target proteins were mainly enriched in interferon gamma signaling, and response to immune." (PMID 35440542, 2022). "STAT1 plays an essential role in the immune response and protects against pathogen infections; thus, STAT1 is generally considered a tumor suppressor." (PMID 35313878, 2022). "STAT1 is involved in cytokine production and is required for the recruitment and activation of T cells in the tumor microenvironment." (PMID 36135194, 2022). "Based on these findings, we propose a model demonstrating the divergent roles of STAT1 signalling in cancer cells and immune cells of the tumour microenvironment." (PMID 35595823, 2022). "Treatment of SMMC7721 xenograft tumors with 125I, EPI, and STAT1-RNAi, performed to further investigate the function of STAT1 on the 125I-induced anti-cancer effect, produced significant suppression of tumor growth by 125I." (PMID 35692770, 2022). "By its capacity to control the immune system and promote tumor immune surveillance, STAT1 has been recognized as a tumor suppressor in breast cancer." (PMID 35163491, 2022). "As discussed for oral cancer, while STAT1, exerts tumor suppressive activities, by integrating the anti-proliferative and pro-cell death signals elicited by interferons, it can also drive tumor promoting activities in stromal cells." (PMID 35844493, 2022).